KIF5A (kinesin family member 5A)
Diseases named in the same sentence as KIF5A in open-access papers (continued):
Sharing a sentence is not in itself a finding about the gene and the disease.
infection (2 papers, 2018 to 2025). The state of being infected such as from the introduction of a foreign agent such as serum, vaccine, antigenic substance or organism. "KIF5A/C isoforms then serve to traffic viral particles along axons, resulting in characteristic recrudescent infection." (PMID 39651860, 2025).
neurodevelopmental disorder (1 paper, 2024). A behavioral and cognitive disorder with onset during the developmental period that involves impaired or aberrant development of intellectual, motor, or social functions. "Mutations targeting distinct domains of the neuron-specific kinesin KIF5A associate with different neurodegenerative/neurodevelopmental disorders, but the molecular bases of this clinical heterogeneity are unknown." (PMID 39333504, 2024).
KIF5A also shares sentences with these, for which no sentence is quoted: Parkinson disease (3 papers); astrocytoma (2); prostate carcinoma (2); spinal muscular atrophy (2); adrenomyeloneuropathy (1); Anxiety (1); Autoimmunity (1); bladder urothelial carcinoma (1); Cerebellar atrophy (1); cerebrotendinous xanthomatosis (1); Charcot-Marie-Tooth disease type 2A (1); cortical dysplasia (1); dementia (1); developmental delay (1); Dystonia (1); esophageal carcinoma (1); familial amyotrophic lateral sclerosis (1); head and neck squamous cell carcinoma (1); hereditary peripheral neuropathy (1); hereditary spastic paraplegia 10 (1); Huntington disease (1); Krabbe disease (1); mental disorder (1); oligodendroglioma (1); Paget disease (1); pancreatic adenocarcinoma (1); paraplegia (1); Parkinsonism (1); peripheral nerve injury (1); retinitis pigmentosa (1).
A further 6 diseases each share a sentence with KIF5A in 1 paper.